CD4 (CD4 molecule)
Diseases named in the same sentence as CD4 in open-access papers (continued):
Sharing a sentence is not in itself a finding about the gene and the disease.
HIV-1 infection (continued). "HIV-1 Nef-specific CD4+ T-cell responses are also important to control HIV-1 viral load and the Nef 66–97 peptide included in the DALIA vaccine was found among the 4 Nef epitopes previously associated with non-progression in HIV-1 infection." (PMID 31498845, 2019). "Moreover, in-depth analyses of CD4+ T-cell counts and HIV-1 diversity evolution indicated that the main difference between single and dual-infected individuals was determined during early HIV-1 infection." (PMID 31484562, 2019). "Due to the development of XGVHD in the HIV-1-infected NCG mice, whether the enriched CCR5-disrupted CD4+ T cell population could confer long-term resistance to HIV-1 infection was not assessed in our humanized mice study." (PMID 31186067, 2019). "Nevertheless, the absence of sequence-identical viral sequences in three out of four of our patients may suggest that clonal proliferation of HIV-1-infected CD4 T cells is not a frequent phenomenon during the earliest stages of HIV-1 infection." (PMID 31227699, 2019). "HIV-1 infection is also restricted by SAMHD1 in resting CD4+ T cells but not in activated T cells." (PMID 31426525, 2019). "The trend observed indicating reduced TLR3 expression on splenic CD4 T cells upon HIV-1 infection could additionally contribute to the lack of HIV-1 RNA recognition." (PMID 30867315, 2019). "Additionally, in contrast to peripheral CD4 T cells, HIV-1 infection does not induce the expression of TLR7 in splenic CD4 T cells or macrophages." (PMID 30867315, 2019). "Interestingly, we observed that CECs, when obtained from the cord blood of mothers with IBD, did not enhance HIV-1 infection in autologous CD4+ T cells—possibly because of their impaired ROS production ability." (PMID 31772057, 2019). "In this review, we discuss how untreated HIV-1 infection disrupts CD4+ T cell homeostasis and how homeostasis is subsequently restored on ART, consistent with ART facilitating the establishment of the majority of the stable HIV-1 reservoir in long-lived CD4+ T cells." (PMID 31507594, 2019). "HIV-1 infection of CER and VAG cells was determined by dual intracellular staining for HIV-1 Gag and epithelial marker cytokeratin 19 (CK19) proteins after exposure to HIV-1 (IIIB or Bal)–HTLV-1-coinfected primary CD4+ T cells (two left panels) or T cell lines." (PMID 29624497, 2018). "It is well known that CD4 counts and viral load in HIV-1 infected individuals, and the rates at which they change, differ over time, which makes it difficult to compare changes in these parameters between two individuals at different periods of their HIV-1 infection." (PMID 30237799, 2018). "Therefore, our results demonstrated that HIV-1 infection increases CD300a expression levels on CD4+CD300a+ cells and that cART does not reverse the upregulation of CD300a expression found in these patients." (PMID 30083165, 2018). "Taken together, our results indicate that during HIV-1 infection there is a decrease in HDL levels along with a persistent inflammatory response, in particular in those individuals with evidence of disease progression (increased HIV RNA load and lower CD4+ T-cells counts)." (PMID 29963050, 2018). "This may reflect the relatively small size of the control groups and/or the fact that HIV-1 infection was not extremely advanced (mean days since diagnosis with acute seroconversion = 764.5, mean CD4 = 482) in our study group." (PMID 29616021, 2018). "Moreover, since both HIV-1 and HTLV-1 can infect the same epithelial cells under these conditions, multiple rounds of HIV-1 infection of epithelial cells is possible through pseudotyping, further facilitating the spread of HIV-1 to intraepithelial CD4+ T cells, macrophages, or dendritic cells." (PMID 29624497, 2018).
HIV-1 infection (continued). "We therefore concluded that infection with SIVcpz strains that are closely related to ancestral HIV-1 results in significantly less or no immune activation and CD4+ T-cell deletion compared with HIV-1 infection, despite having similar levels of plasma viral load." (PMID 29615603, 2018). "As expected, expression of HAFv1n in U87MG CD4/CXCR4 cells did not inhibit HIV-1 infection." (PMID 28747499, 2017). "Thus eCD4-Ig is qualitatively different from CD4-Ig or neutralizing antibodies in its ability to mediate ADCC, and it may be uniquely useful in treating HIV-1 infection or reducing the reservoir of latently infected cells." (PMID 29253851, 2017). "Successful prevention of virus acquisition may require a balance in antibody and CD4+ T cell responses in which changes in levels of virus-specific CCR5+ CD4+ T cells, preferential targets for HIV-1 infection, do not mute the effect of protective antibodies." (PMID 29021394, 2017). "In absence of HIV-1 infection, overexpression of let-7i still protected CD4+ T cells against apoptosis, which might be triggered by activation-induced cell death (AICD)." (PMID 27145859, 2016). "This suggests that LPS may in part explain why gram-negative bacteria were particularly efficient at enhancing HIV-1 infection of LP CD4 T cells." (PMID 26762145, 2016). "Altogether, it is believed that normal CD4 T cell functions in GALT are significantly compromised in HIV-1 infection and may not be completely normalized by ART." (PMID 27822211, 2016). "However, it is not known whether ART initiated during the early phase of infection prevents the establishment of abnormal phenotypic features previously reported in CD4+ and CD8+T cells during chronic HIV-1 infection." (PMID 27281071, 2016). "However, our results show that levels of IL7 and CCL21 actually decrease in lymph nodes under advanced HIV-1 infection, which is consistent with our perspective that peripheral recovery of CD4+ T cells does not represent their recovery in lymph nodes." (PMID 27011165, 2016). "Our model also makes several assumptions that may not fully reflect details of HIV-1 infection, such as assuming that infected and uninfected CD4 T cells have equivalent division rates." (PMID 27010978, 2016). "Here we report activated CD4+ T cells without SAMHD1 expression were severely reduced, and SAMHD1 in CD4+ T cells became susceptible to SIV-Vpx mediated degradation during chronic HIV-1 infection, which was absent from uninfected donors." (PMID 27922067, 2016). "The corresponding values for the LA group were 0.43 (baseline), 0.81 (12 months; P < 0.01), and 0.83 (P < 0.0001); thus the median CD4+/CD8+ cell ratio never reached the value of 1 or above in the group that received ART during the chronic phase of HIV-1 infection." (PMID 27281071, 2016). "Furthermore, by knocking down the expression of IL-2, we found that the let-7i-mediated CD4+ T cell resistance to apoptosis during HIV-1 infection was dependent on IL-2 signaling rather than an alternative CD95-mediated cell-death pathway." (PMID 27145859, 2016). "CD4+ cell counts were also observed to be higher in adult women with and without HIV-1 infection." (PMID 29083382, 2016). "When introduced into primary cells, CD4 T cells expressing C34-conjugated coreceptors exhibited physiologic responses to T cell activation while inhibiting diverse HIV-1 isolates, and cells containing C34-conjugated CXCR4 expanded during HIV-1 infection in vitro and in a humanized mouse model." (PMID 27855210, 2016). "Lamina propria (LP) mononuclear cells were infected with CCR5-tropic HIV-1BaL or mock infected, exposed to high (3 gram-negative) or low (2 gram-positive) abundance HAMB or control gram-negative Escherichia coli and levels of productive HIV-1 infection and CD4 T cell depletion assessed." (PMID 26762145, 2016). "Furthermore, ISG induction in primary targets of HIV-1 infection, such as human CD4+ T cells, has not been evaluated." (PMID 26849062, 2016).
HIV-1 infection (continued). "However, in the absence of HIV-1 infection, decreased CD4+ cell counts with increased PPF grades score have been observed, in individuals who had PPF grades D/E and had lower median CD4+ cell counts." (PMID 25948238, 2015). "Therefore the increase in HPV prevalence is an early event after HIV-1 infection and is not correlated with a drop in circulating CD4+ cells." (PMID 26239348, 2015). "However, a recent study from Siliciano’s group, demonstrated that antiretroviral therapy fails to eradicate HIV-1 infection because latent proviruses persist in resting CD4+ T cells despite the low levels of CpG methylation in LTRs." (PMID 25875202, 2015). "mDC (CD1c+), SLAN+ DC and CD14+ monocytes were most efficient in stimulating proliferation of CD4+ T-cells during syngeneic culture and in generating post-integration latent infection in non-proliferating CD4+ T-cells following HIV-1 infection of APC-T cell co-cultures." (PMID 26362311, 2015). "Taken together, we propose a model whereby HIV-1 infection primes T cells for receptor-mediated, calcium-dependent mitochondrial translocation to the contact zone, thus creating a localized environment that supports efficient HIV-1 VS formation and transmission between CD4 T lymphocytes." (PMID 25320323, 2015). "While early epidemiological studies showed reduced survival in HIV-infected IDU patients compared to HIV-infected non IDU controls, more recent studies have suggested that progression of HIV-1 infection in IDU as reflected by decline in CD4+ T-cell counts, is equivalent to non-IDU controls." (PMID 26925299, 2015). "Because CD4+ and CD8+ T-cell responses detected by ICS were previously reported not to be associated with risk of HIV-1 infection and there were a small number of infected and uninfected participants with available data, we refrained from further quantitative analysis of ICS responses." (PMID 25369172, 2014). "This inhibition is likely due to the presence of CD4 molecules in these extracellular vesicles, since equivalent amounts of exosomes prepared from a T cell line that does not express CD4 were not able to inhibit HIV-1 infection." (PMID 25423108, 2014). "To investigate whether GPR15 expression on these T cell subsets is altered in the context of HIV-1 infection, we analyzed surface expression of GPR15 on CCR7+CD45RA− central memory, CCR7−CD45RA− effector memory and CCR7+CD45RA+ naïve CD4+ T cells from healthy donors and HIV-1 infected individuals." (PMID 24558379, 2014). "The proportion of cells, likely CD4+ T-cells, producing IFN-γ without stimulation by exogenous antigen appears to carry information beyond T-cell activation and baseline characteristics that predict risk of HIV-1 infection." (PMID 25369172, 2014). "Therefore, the existence of a relationship between the number of CD4+ T-cells and PON1 activity, which would be directly related to the best course of HIV-1 infection, may be suggested." (PMID 24719500, 2014). "It has been demonstrated that inhibitory receptors, such as PD-1, are expressed at elevated levels on both CD4+ and CD8+ T-cells in subjects with chronic HIV-1 infection, and diminished function of these cells may contribute to ineffective control of HIV-1 replication." (PMID 23902750, 2013). "Of 607 individuals initiating cART within one year of seroconversion and with CD4 counts >350 cells/μl, 338 (55.7%) were from the PRIMO cohort in France, reflecting the policy in this country during the 1996–2004 period to systematically treat individuals presenting during primary HIV-1 infection." (PMID 23936260, 2013). "DC-SIGN facilitates HIV-1 infection independent of CD4 and/or co-receptors." (PMID 24391808, 2013). "However, since cultured primary CD4+ T cell subsets do not retain all of their in vivo attributes, the dynamics of each subset on HIV-1 infection are poorly understood." (PMID 24339781, 2013).
HIV-1 infection (continued). "Finally, it has also been shown that HIV-1 infection of trophoblasts is independent of CD4 but, at least partly, relies on HSPG." (PMID 24312095, 2013). "The numeric distribution and functional role of LAP+ CD4 Treg during HIV-1 infection is not known." (PMID 23382678, 2013). "The reason why LM being a strong TLR2 agonist in the HEK293 assay, does not co-stimulate or significantly increase HIV-1 infection in primary CD4+ T cells may be related to a dominant TCR inhibitory effect of this glycolipid." (PMID 24282561, 2013). "A role of tetherin in IFN-α pathway in HIV-1 infection is further supported by the observation that pegylated IFN-α/ribavinin combination therapy for HIV/hepatitis C virus co-infected individuals decreased HIV-1 viral load, which is correlated with an increase in tetherin levels in CD4+ T cells." (PMID 24167505, 2013). "This antiviral drug will prevent HIV-1 infection of DCs (i.e. cis-infection) without altering their ability to transmit virions located on their surface and/or within their endosomal apparatus (i.e. trans-infection) to CD4+ T cells." (PMID 23844079, 2013). "The results of our previous studies with DS are consistent with previously published studies, which demonstrated that DS could enhance HIV-1 infection in monocyte-derived macrophages but not in CD4+ T lymphocytes." (PMID 22281044, 2012). "Further elucidating the mechanisms of SAMHD1-mediated HIV-1 restriction in non-cycling myeloid cells and resting CD4+ T-cells may help develop new therapeutic approaches against HIV-1 infection." (PMID 23092163, 2012). "HIV-1 infection of CD4+ T cells is not identical to its infection of macrophages." (PMID 23110561, 2012). "By comparing blood and pericardial fluid from TB patients with and without HIV-1 infection, we show that the majority of CD4+ T cells at the disease site of HIV-1-uninfected patients express CCR5 and are of effector memory and terminally differentiated phenotype." (PMID 22215422, 2012). "Guidance on optimal timing for initiation of antiretroviral therapy (ART) is still evolving, but the contribution of HIV-1 infection to excess mortality at CD4 cell counts above thresholds for HIV-1 treatment has not been fully described, especially in resource-poor settings." (PMID 23130818, 2012). "Unlike sCD4 and D1D2, 2DLT did not enhance HIV-1 infection in CD4-/CCR5+ cells." (PMID 23217195, 2012). "Let 7b and Let 7g microRNAs were shown to be significantly decreased in PBMCs and CD4+ T cells of HIV-1 infected patients as compared to healthy controls or patients who can naturally control HIV-1 infection (Long Term Non-Progressors, LTNP; and elite suppressors)." (PMID 23202492, 2012). "DCs are refractory to productive HIV-1 infection, which may explain the lack of significant activation of CD4+ T cells in cocultures." (PMID 22479639, 2012). "Although guidelines for the diagnosis and treatment of HIV-1 infection recommend starting therapy when number of CD4+ T cells is < 500-350/μL, it is not uncommon in clinical settings to observe a later initiation of HAART in patients who present with advanced HIV-1 disease." (PMID 22166160, 2011). "We have shown that macrophages isolated from normal human small intestine are highly refractory to productive HIV-1 infection, supporting observations that memory CD4+ T cells rather than macrophages are the predominant mononuclear target cell in the intestinal mucosa during primary HIV-1 infection." (PMID 21637819, 2011). "Because cystatin B is localized predominantly in the cytoplasm, while cystatin C is generally located in late endosomes or secreted, and because cystatin C did not affect the CD4-dependent HIV-1 infection in our study, the roles of cystatins B and C in HIV-1 infection should be different." (PMID 21541353, 2011). "We investigate whether the negative effects of HIV-1 infection and aging on the naïve CD4+ T-cell compartment are additive or interactive." (PMID 21298072, 2011).
HIV-1 infection (continued). "Interestingly, it was also reported that Vpr's nuclear localization and consequent G2 arrest properties are important in HIV-1 infection of primary CD4+ T-cells irrespective of proliferative status (reviewed in:)." (PMID 21489275, 2011). "However, the endosome acidification inhibitors do not suppress CD4-dependent HIV-1 infections, but rather enhance them." (PMID 21541353, 2011). "The changes observed in the abundance of CCR5 and CXCR4 chemokine receptors on CD4+ T-cells and of cytokines/chemokines during the natural course of non-clade B HIV-1 infection suggests that the phenotypic switch is not driven by changes in the levels of these receptors or anti-HIV cytokines." (PMID 21655330, 2011). "However, in HIV-1 infection, lymphoid tissue also represents an important site for viral replication, and the interaction between APC and CD4+ T cells may enhance viral replication by multiple mechanisms." (PMID 21752277, 2011). "Indeed, a significant number of patients with a more active form of HIV-1 infection never underwent off-treatment CD4 monitoring, but immediately started antiretroviral therapy." (PMID 21494630, 2011). "By contrast, the predominant mechanism for the inhibition of the R5 HIV-1 infection by the A120 mAb is most likely due to the production of the CCR5-binding β-chemokines, especially MIP-1α, from activated T cells and monocytes leading to down-modulation of CCR5 expression on CD4+ T cells." (PMID 22018245, 2011). "Given that RA and HIV-1 infections share common features such as a chronic inflammatory condition and polyclonal immune hyperactivation status, we hypothesized that HIV-1 could promote DCIR expression in CD4+ T cells." (PMID 21085612, 2010). "Contrary to CD4+ T cells, HIV-1 infection is generally not lytic for these cells." (PMID 20380694, 2010). "While there was a clear pattern of CD4 T cell decline in un-treated mice, their levels were stable in both groups of mice receiving raltegravir or maraviroc further confirming the absence of HIV-1 infection in these mice." (PMID 21203568, 2010). "However, a recent study reported that the deletion of all the nuclear localization signals described in HIV-1 proteins did not abrogate HIV-1 infection of resting CD4+ T cells and Mφ." (PMID 20374633, 2010). "In addition, our study demonstrated for the first time the presence of CD4 mRNA in fecal specimens of HIV-1 infected subjects, which could be used to assess GALT pathogenesis in HIV-1 infection." (PMID 19799780, 2009). "Therefore the key to deciphering this mystery may lie with the answer to why these HIV-specific CD4+ and CD8+ T cell responses disappear during acute HIV-1 infection." (PMID 19165342, 2009). "Elucidating cellular mechanisms that determine why some, but not all, CCR5-expressing CD4+ T cells are permissive to R5-tropic HIV-1 infection could provide clues to identify natural cellular HIV-1 barriers." (PMID 17465678, 2007). "During acute HIV-1 infection, HIV-specific CD8+ T-cells were strongly activated, and, intriguingly, activation of the CD8+ T-cell compartment as a whole was particularly high, reaching to levels of 80%–90%, in contrast to CD4+ T-cells, which show much less activation." (PMID 14966528, 2004). "However, whether PLIN3 plays a role in HIV-1 infection of primary CD4+ T cells has not been reported." (PMID 41085277, 2025). "Nonetheless, it is currently unknown whether viremic nonprogressors (VNPs), a very rare phenotype characterized by a paradoxically nonpathogenic HIV-1 infection and sustained CD4+ T-cells counts despite continuous viral load, may eventually lose CD4+ homeostasis (LoH)." (PMID 34668779, 2022). "While still not fully elucidated, the inability to completely clear an HIV-1 infection could largely be due to accessory proteins, such as Vpu, that aid in immune system evasion through mechanisms such as the downmodulation of CD4, BST-2/Tetherin, and inhibitory effects on ADCC." (PMID 35458546, 2022).